CYP19A1 (cytochrome P450 family 19 subfamily A member 1)
Diseases named in the same sentence as CYP19A1 in open-access papers (continued):
Sharing a sentence is not in itself a finding about the gene and the disease.
endometrial cancer (23 papers, 2009 to 2025). Primary or metastatic malignant neoplasm involving the endometrium (mucous membrane that lines the endometrial cavity). "Consistent with its function, increased CYP19A1 expression was associated with increased endometrial cancer risk in our study." (PMID 34675350, 2021). "Two candidate endometrial cancer susceptibility genes (CYP19A1 and EEFSEC) were prioritized using both S-MultiXcan-colocalization and MR-JTI approaches." (PMID 34675350, 2021). "For example, the genes encoding drug targets of tamoxifen (ESR1) and aromatase inhibitors (CYP19A1) have been linked to genetic variation associated with risk for breast and endometrial cancer, diseases that are treated using these drugs." (PMID 29270124, 2017). "We have also observed that circulating estradiol and genetic variation in CYP19A1, the gene encoding aromatase, have similar effects on endometrial cancer risk, suggesting that this variation mediates its effects by up-regulating CYP19A1 expression." (PMID 28487654, 2017). "We conducted the largest comprehensive genetic study to date of SNPs across the CYP19A1 hormone metabolism gene and their associations with both endometrial cancer risk and circulating E2 concentration." (PMID 26574572, 2016). "In conclusion, we have confirmed at a genome-wide-level of significance the association between endometrial cancer and variants within the CYP19A1 gene, and shown that all of the reported associations can be explained by a single risk peak." (PMID 26574572, 2016). "We analyzed 2937 single nucleotide polymorphisms (SNPs) in 6608 endometrial cancer cases and 37 925 controls and report the first genome wide-significant association between endometrial cancer and a CYP19A1 SNP (rs727479 in intron 2, P=4.8×10−11)." (PMID 26574572, 2016). "Candidate gene studies have reported CYP19A1 variants to be associated with endometrial cancer and with estradiol (E2) concentrations." (PMID 26574572, 2016). "Our findings based on a genetic variant in the CYP19A1 gene provide support that elevated serum E2 levels are causally linked to higher risk of ER-positive breast cancer and endometrial cancer, particularly of the endometrioid histology, suggesting a role of E2 in hormone-sensitive cancers." (PMID 34601599, 2022). "To prioritise the genes identified by JTI, we performed a Mendelian randomization (MR) causal inference analysis in the respective tissues using MR-JTI, providing five candidate endometrial cancer susceptibility genes: CYP19A1, SNX11, AC021755.3, EEFSEC, and EIF2AK4." (PMID 34675350, 2021). "This is the first study to look at the CYP19A1 endometrial cancer association by histology." (PMID 26574572, 2016). "Our findings based on the CYP19A1 variant corroborate the results of a pooled analysis of 4998 endometrial cancer cases and 8285 controls from 10 studies in the Epidemiology of Endometrial Cancer Consortium as well as a study based on 6608 endometrial cancer cases and 37 925 controls from 4 studies." (PMID 34601599, 2022). "In this study, we identified two SNPs, rs17601876 in CYP19A1 and rs2900478 in SLCO1B1, that were associated with endometrial cancer." (PMID 40141105, 2025). "The associations between endometrial cancer and variants in or around HNF1B, CYP19A1, SOX4, MYC, KLF and EIF2AK found in earlier GWAS were then replicated in the latest and largest GWAS." (PMID 32066633, 2020). "We found that single nucleotide polymorphisms (SNPs) in HNF1B, KLF, EIF2AK, CYP19A1, SOX4 and MYC were strongly associated with incident endometrial cancer." (PMID 32066633, 2020). "Imputation and post-imputation QC identical to that performed in the endometrial cancer analysis resulted in 1956 SNPs across the CYP19A1 region, of which 100 had been genotyped." (PMID 26574572, 2016).
endometrial cancer (continued). "Furthermore, the ten CYP19A1 SNPs genotyped have been reported to influence hormone estradiol levels in postmenopausal women, predict clinical outcome in metastatic breast cancer patients treated with letrozole, and significantly increase risk of colon and endometrial cancer development." (PMID 25647083, 2015). "The associations of CYP19A1, SKAP1, HEY2, EEFSEC, and EVI2A were supported by colocalization of eQTL and GWAS signals in at least one of the relevant tissues; thus, these five genes were prioritized as candidate endometrial cancer susceptibility genes." (PMID 34675350, 2021). "In tissue samples, several reports showed immunohistochemical staining for CYP19A1 in paraffin sections of endometrial cancer, where both stromal and epithelial cells were stained, and several reports have shown a lack of specific staining (for review, see Rižner, 2013)." (PMID 28674494, 2017). "The use of AIs in the treatment of endometrial cancer is not well established despite the pleiotropic effect of CYP19A1 on endometrial cancer risk." (PMID 28487654, 2017). "Moreover, CYP19A1 variation may have clinical implications for anti-estrogen therapies used in the treatment of breast and endometrial cancer." (PMID 28487654, 2017).
Infertility (20 papers, 2005 to 2025). "Considering these results, we analysed the distribution of CYP19A1 codon 39 genotypes in infertile women and in fertile women, nevertheless the related cause of infertility (n = 201)." (PMID 37107315, 2023). "In the present study, we have evaluated if women carriers of CYP19A1 codon 39 Trp/Arg (T/C) polymorphism (rs2236722) present increased susceptibility to infertility factors." (PMID 37107315, 2023). "Here, we aim to investigate the incident of polymorphisms in the CYP19A1 gene that increases PCOS risk with infertility." (PMID 35205347, 2022). "On the other hand, they discovered that the AA genotype of the CYP19A1 polymorphism was strongly associated with an increased risk of endometriosis and infertility in the population." (PMID 35205347, 2022). "Because each individual’s SNP profile is unique, more investigations in various populations are required to resolve the controversy surrounding the effect of CYP11A1, CYP17A1, and CYP19A1 polymorphisms on infertility and PCOS." (PMID 35205347, 2022). "The implications of our findings might suggest that CYP19A1 is probably the susceptible gene that contributes to infertility." (PMID 35205347, 2022). "Hence, dysregulation of ERbeta and CYP19A1 expression has been associated with increased probability of infertility." (PMID 34684636, 2021). "Moreover, overexpression of CYP19A1 in male mice was shown to increase estrogen production and cause infertility in adulthood." (PMID 34684636, 2021). "Lycium barbarum caused an up-regulation in the expression of CYP19A1, CYP17A1, AR, and SRD5A2, which in turn increased the level of serum testosterone to combat infertility." (PMID 40149961, 2025). "Certain polymorphisms in the CYP19A1 gene have been linked to an increased risk of (PCOS), infertility, and reproductive cancers such as breast, endometrial, and ovarian cancers." (PMID 39062040, 2024). "The result of this finding suggests that CYP19A1 contributes to infertility through the adverse effects of androgens on metabolism and inflammation impairing ovulation." (PMID 37371662, 2023). "We analysed the two-way combination of GSTM1 and CYP19A1 genotypes and found that when GSTM1 is present, there is a significant association with infertility risk (OR 3.216; 95% CI (1.715–6.031; p < 0.001)." (PMID 37107315, 2023). "Lastly, we analysed the distribution of CYP19A1 codon 39 genotypes in infertile women with tubal pathologies and in fertile women." (PMID 37107315, 2023). "We evaluated the occurrence of polymorphisms in various ethnicities in the CYP11A1, CYP17A1, and CYP19A1 genes and their efficacy on increasing PCOS risk with infertility." (PMID 35205347, 2022). "We have chosen the genetic polymorphism of the genes involved in the steroidogenesis pathway as the candidate genetic variants that are susceptible to infertility between females with PCOS, focusing on CYP11A1, CYP17A1, and CYP19A1." (PMID 35205347, 2022). "Additionally, VDR knockout mice were infertile and had decreased folliculogenesis and CYP19A1 expression, whereas after supplementing with E2, the uterine weight increased." (PMID 37232725, 2023). "Additionally, we analysed the distribution of CYP19A1 codon 39 genotypes in infertile women with PCOS and in fertile women." (PMID 37107315, 2023). "Moreover, cancer studies have revealed that CYP19A1 also plays a role in obesity and infertility in Chinese women." (PMID 35205347, 2022). "In conclusion, our study strongly suggests that the CYP11A1, CYP17A1, and CYP19A1 genes might significantly enhance the probability of developing PCOS with infertility." (PMID 35205347, 2022). "Male Cyp19a1 and ERα KO mice are infertile as a result of the defective spermatogenesis." (PMID 34679897, 2021).
Infertility (continued). "The expression of the CYP19A1 (aromatase) mRNA was found to be 14.5-fold higher in the mid-secretory phase, eutopic endometrium of infertile patients with mainly severe endometriosis of rectovaginal, peritoneal and ovarian subtypes compared with the control subjects." (PMID 31878927, 2019). "A comparison of the levels of the target transcripts between samples obtained from control fertile (group 1A) and control infertile (group 1B) patients revealed higher (P < 0.05) CYP19A1 expression in the control fertile patients than in control infertile patients." (PMID 31878927, 2019). "This work highlights the great influence of CYP19A1 codon 39 Trp/Arg (T/C) polymorphism (rs2236722) and GSTM1 and GSTT1 polymorphisms in female fertility and brings to discussion the value of assessing low penetrance polymorphisms to prevent infertility in the general population of women." (PMID 37107315, 2023).
hyperandrogenism (19 papers, 2009 to 2025). Excessive secretion of androgens from the adrenal glands or gonads. "In the present study, administration of Zea and MgONPs alike was found to downregulate Cyp19a1 in ovarian tissue, which caused hyperandrogenism." (PMID 38790905, 2024). "Normalizing CYP19A1 expression after surgery is linked to increased estrogen production, decreased hyperandrogenism, and improved menstrual regularity." (PMID 39857648, 2024). "The frequency of genotypes for the CYP19A1 rs700518 polymorphism in women with hyperandrogenism was compared." (PMID 35743606, 2022). "Furthermore, animal experiments have validated that melatonin can regulate key genes associated with hyperandrogenism, including AR and CYP19A1." (PMID 40838208, 2025). "Pathogenic variants in the CYP19A1 gene lead to aromatase deficiency, causing androgen excess." (PMID 38812815, 2024). "The study showed that the CYP19A1 gene rs700518 polymorphism may be associated with the distribution of adipose tissue in young women with hyperandrogenism." (PMID 35743606, 2022). "In conclusion, the study showed that the CYP19A1 rs700518 polymorphism may be associated with the distribution of adipose tissue in young women with hyperandrogenism." (PMID 35743606, 2022). "Therefore, the aim of the study was to assess the effect of the CYP19A1 gene polymorphism on selected markers of bone metabolism and hormonal parameters in women with hyperandrogenism." (PMID 35743606, 2022). "This shows how orexigenic peptides contribute to the hyperandrogenism associated with PCOS, which, based on these results, we presume is mediated by Cyp19a1 and testosterone factors." (PMID 37147728, 2023). "In our group of women with hyperandrogenism, we observed an association of the adipose tissue distribution indices (BAI, AG, and VF) with the GG, AA, and AG genotypes of the CYP19A1 rs700518 polymorphism." (PMID 35743606, 2022). "Taking into account that CYP19A1 mRNA increased under hyperandrogenism treatment, we hypothesized that AR may bind to the promoter of CYP19A1 gene to regulate aromatase expression." (PMID 40898340, 2025). "CYP19A1 has also been identified as an immediate objective of BMAL1 in PBMCs, and low expression of BMAL1 increases the activity of 5a-reductase, exacerbating hyperandrogenism." (PMID 40838208, 2025). "Pathophysiological functions of genes are primarily responsible for the synthesis of proteins that have role in PCOS before hyperandrogenism including GnRHR, FSHβ, FSHR, LHCGR, CYP19A1, HSD17B, AR and SHBG, and their effects in PCOS of human have been confirmed." (PMID 30944702, 2019).
Insulin resistance (16 papers, 2010 to 2025). Increased resistance towards insulin, that is, diminished effectiveness of insulin in reducing blood glucose levels. "Mice globally deficient in aromatase (Cyp19a1 KO) are more prone to aging-associated increase in abdominal obesity and insulin resistance." (PMID 41180177, 2025). "In men and women combined, CYP19A1 alleles associated with higher E2 levels were associated with lower degrees of insulin resistance." (PMID 29325096, 2018). "Furthermore, men with aromatase deficiency resulting from an inactivating mutation of the CYP19A1 gene are overweight or obese, and display and insulin resistance, which often improves with estrogen replacement therapy." (PMID 29325096, 2018). "For example, single nucleotide polymorphisms (SNPs) in the gene CYP19A1, encoding for the aromatase enzyme that is involved in the final step of estrogen synthesis in both men and postmenopausal women, are associated with hypertension, apolipoprotein B levels, and insulin resistance." (PMID 39940335, 2025). "We found that SERT deletion or pharmacological inhibition suppresses ovarian Cyp19a1 expression, reducing circulating 17β-estradiol levels, leading to abnormal fat accumulation, insulin resistance, and glucose intolerance." (PMID 28442777, 2017). "Male ArKO mice as well as men with CYP19A1 defects show insulin resistance and hyperglycemia." (PMID 34572151, 2021). "Here, we demonstrated that SERT−/− mice display abnormal fat accumulation in both white and brown adipose tissues, glucose intolerance and insulin resistance while exhibiting suppressed aromatase (Cyp19a1) expression and reduced circulating 17β-estradiol levels." (PMID 28442777, 2017). "Quercetin, a flavonoid found in P. dioscoridis extract, increases CYP19A1 and CYP11A1 expressions leading to elevating estrogen levels in letrazole-induced PCOS mice model, in addition to improving insulin resistance through its antioxidant properties." (PMID 40569946, 2025).
breast tumors (13 papers, 2011 to 2025). "One study has reported that the T-allele of rs10046 is associated with elevated levels of CYP19A1 mRNA in breast tumors." (PMID 29363090, 2018). "Amplification of the CYP19A1 gene is also found in AI-resistant breast tumors (21.5% of AI-treated and < 2% of primary tumors), leading to increased aromatase activity, estrogen availability, and consequent ER signaling." (PMID 36045911, 2022). "While ESR1 amplification has been an intense area of investigation underlying endocrine therapy resistance a study focusing on genomic aberrations of the drug target of AIs, aromatase (CYP19A1), has deepened our understanding of endocrine-refractory ER+ breast tumors." (PMID 31106278, 2019). "We also report that DVL enters the nucleus and localizes to at least two different CYP19A1 promoters (pII and I.4) previously reported to drive overexpression in breast tumors and to a very distal CYP19A1 placental promoter (I.1) that remains poorly characterized." (PMID 30479694, 2018). "The up-regulation of Cyp19A1 gene expression via COX-2 was shown to be dependent on PGE2 synthesis and cAMP signaling in undifferentiated rat granulosa cells or in human breast tumor cells." (PMID 21352547, 2011). "CYP19A1 mRNA levels in both MMTV-PyMT-driven breast tumors and normal mammary tissue were substantially high with no apparent differences between the two groups." (PMID 36614200, 2023). "We also found non-significant positive correlations of CYP19A1 mRNA expression with ER status and with ESR1 mRNA expression in breast tumors." (PMID 29363090, 2018).
diabetes (12 papers, 2014 to 2026). "CYP19A1 is a potential target for diabetes treatment and can play an important role in this process." (PMID 38338442, 2024). "The results showed that the expression of RORA and CYP19A1 was significantly decreased in maternal diabetes (STZ/WT) group compared to the CTL/P-VEH group." (PMID 35027651, 2022). "Sulindac can treat diabetes in mice by activating CYP19A1 to synthesize estrogen, and multiple clinical data show that the CYP19A1 gene deeply affects plasma zinc levels, urinary zinc levels, susceptibility, and other issues in Chinese type 2 diabetic populations." (PMID 38338442, 2024). "By affecting cyp19a1 methylation status and alternative splicing, paternal diet coordinates androgens’ metabolism in the progeny affecting it in a sexually dimorphic way and promoting hypoandrogenism, growth retardation and diabetes in male pups." (PMID 40604316, 2024). "PheWAS analysis of the eight candidate susceptibility genes revealed that four candidate genes (CYP19A1, EIF2AK4, EVI2A and SNX11) associated with 56 traits related to seven phenotypic categories: anthropometric, bone health, cardiovascular, diabetes, hematopoiesis, liver function, and sex hormones." (PMID 34675350, 2021). "We assessed methylation of the −383 to −281 bp region of the PPARG promoter as PPARγ suppresses CYP19A1 expression in breast tissues in culture, and relative hypermethylation of this region has been associated with reduced PPARγ expression in hyperandrogenic PCOS and diabetes models." (PMID 24649863, 2014). "We first evaluated gene expression from IEC, and the results showed that maternal diabetes (STZ/WT) significantly decreased mRNA levels of RORA, CYP19A1 and SOD2, respectively, compared to the CTL/WT group." (PMID 35164690, 2022). "The results showed that maternal diabetes (STZ/WT) significantly decreased the expression of RORA, CYP19A1, and SOD2 compared to the control (CTL/WT) group, and prenatal RORA deficiency mimicked the effect of maternal diabetes." (PMID 35027651, 2022). "We first evaluated gene expression in the amygdala, including mRNA and protein levels, and found that maternal diabetes (STZ/P-VEH) significantly decreased the expression of RORA, CYP19A1, and SOD2 compared to the control (CTL/WT) group." (PMID 35027651, 2022). "The results showed that maternal diabetes (STZ/VEH) significantly decreased the mRNA levels of RORA, CYP19A1 and SOD2 (P < 0.0001) compared to the CTL/VEH group; MnTBAP treatment (STZ/MnTBAP) completely, while STZ/SR1078 treatment partly (P < 0.01), reversed this effect." (PMID 35164690, 2022). "In addition, we evaluated gene expression in the hypothalamus and hippocampus, and the results showed that maternal diabetes (STZ/VEH) significantly decreased expression of RORA and CYP19A1 in both the hypothalamus and hippocampus compared to the CTL/VEH group." (PMID 35164690, 2022).